STAR (steroidogenic acute regulatory protein)
Diseases named in the same sentence as STAR in open-access papers (continued):
Sharing a sentence is not in itself a finding about the gene and the disease.
tumor (continued). "Additionally, cell-cell communication analysis revealed that in chemotherapy-resistant patients, STAR + cells interact with tumor cells through Wnt signaling, specifically via ligand-receptor pairs such as WNT7A-FZD6/FZD3-LRP6/LRP5, components of the canonical Wnt pathway." (PMID 40098624, 2025). "Importantly, StAR, by itself, was found to enhance E2 synthesis in BC cells, signifying that it could promote breast tumorigenesis and that it acts as a tumor promoter or oncogene." (PMID 39201419, 2024). "It is important to note that the data presented here suggest that constitutive STAR may have a role distinct from hormone-induced STAR in MA-10 mouse tumor Leydig cells and, at present, it is unknown whether this role may be consistent among normal Leydig cells and those from other species." (PMID 33670702, 2021). "Notably, STAR + cells in chemotherapy-sensitive patients exhibited higher enrichment in these pathways compared to resistant patients, suggesting that STAR + cells may enhance chemotherapy efficacy by regulating metabolic processes that increase tumor vulnerability to platinum-based drugs." (PMID 40098624, 2025). "Several genes, such as TMPRSS4, STAR, ST7L, HAS3, FGFR3, CASZ1 and HR, were found to have gene expression changes at the very earliest stages of tumor thickening." (PMID 18442402, 2008). "Furthermore, to investigate the behavior of STAR + cells in metastatic SOC lesions, we analyzed metastatic tumor samples." (PMID 40098624, 2025). "We generated STAR knockout (KO) MA-10 mouse tumor Leydig cells and showed that STAR KO cells failed to form progesterone in response to dibutyryl-cAMP and to TSPO drug ligands, but not to 22(R)-hydroxycholesterol, which is a membrane-permeable intermediate of the CYP11A1 reaction." (PMID 33670702, 2021). "The clusters 1, 7 and 8 highly expressed steroidogenic genes STAR as well as tissue remodeling genes HAS1, ADAMTS1 and ADAMTS4, consistent with theca-stromal cells from ovary, which might be included from non-tumor tissues from ovaries." (PMID 34257564, 2021). "Consistent with this hypothesis, and even though StAR expression may not completely reflect the degree of PKA activity, our data suggest that decreased PKA signalling is associated with more aggressive tumours that exhibit higher levels of WNT target genes expression in ACC patients." (PMID 27624192, 2016). "The expression level of STAR was positively correlated with the infiltration levels of CD4+ T cells, but not with tumor purity and the infiltration levels of CD8+ T cells, dendritic cells, B cells, macrophages, and neutrophil." (PMID 34868460, 2021).
cancer (18 papers, 2011 to 2025). A tumor composed of atypical neoplastic, often pleomorphic cells that invade other tissues. "The mechanism underlying mitochondrial cholesterol accumulation in cancer cells is poorly understood, even though StAR regulates the transport of intra-mitochondrial cholesterol." (PMID 35740335, 2022). "TCGA hormone responsive cancer datasets were analyzed for identifying mutation(s) in the StAR gene, which has been shown to affect the biological activity of the StAR protein in steroid biosynthesis." (PMID 31060224, 2019). "However, one mutation in the StAR gene was identified in each of the following cancers: colorectal (one out of 223 tumors; 0.45%), pancreatic (one out of 150 tumors; 0.67%), and ovarian (one out of 316 tumors; 0.32%)." (PMID 31060224, 2019). "In combination with BLM for cancer, abnormal expression of STAR, CYP11A1, and HSD3B1 led to hormone secretion disorder." (PMID 38137018, 2023). "SAM68 is a nuclear RNA-binding protein belonging to the signal transduction and activation of RNA metabolism (STAR) family, and evidence in the literature has linked SAM68 to tumorigenesis and progression of different cancers." (PMID 35008409, 2022). "GAPDH expression showed the highest fold-change (FC), and STAR had the lowest fold-change among 30 cancer types." (PMID 33917859, 2021). "As determined by exome sequencing, no mutations in the StAR gene were observed in breast (982 tumors) and prostate (499 tumors) cancers, suggesting StAR is functionally active in mobilizing cholesterol to the mitochondria." (PMID 31060224, 2019). "Thus, by increasing the factors that play a key role in the immune-inflammatory cancer network, StAR can promote progression of ER+/PR+ BCs." (PMID 35740335, 2022). "The hypothesis that estrogen and/or androgen sensitive cancers involve gain of function of StAR in the transport of cholesterol, and thereby influence hormone sensitive cancers, was examined." (PMID 31060224, 2019). "SMARCA1, a chromatin remodeling gene, has been reported to stimulate steroidogenic acute regulatory (StAR) protein expression through association with the StAR promoter, and SMARCA1 knockdown causes significant growth inhibition and induces apoptosis of cancer cells." (PMID 22272226, 2012). "In addition, several STAR signaling pathways were found to be associated with oncogenesis, such as the PI3K–Akt signaling pathway (p = 0.00017), Notch signaling pathway (p = 0.0078), transcriptional misregulation in cancer (p = 0.021), and Hippo signaling pathway (p = 0.042)." (PMID 35223782, 2022). "The overexpression of StAR has been shown to affect toll-like receptor 3 (TLR3), TLR6, and lymphotoxin alpha (LTα) activities, which contribute to various cancers." (PMID 35740335, 2022).
infection (8 papers, 2006 to 2022). The state of being infected such as from the introduction of a foreign agent such as serum, vaccine, antigenic substance or organism. "The effects of StAR overexpression on lipid metabolism, inflammation and NO bioavailability were investigated after infection with recombinant adenovirus encoding StAR in RAECs." (PMID 23170972, 2012). "Experimental infection of roosters with NDV also decreased the expression (P < 0.05) of StAR in the testes compared to roosters in the control group." (PMID 32600413, 2020). "Real-time quantitative PCR analysis showed that StAR mRNA level increased by 708 to 6560 folds compared with the Ad-EGFP group using different virus multiplicity of infection (MOI)." (PMID 23170972, 2012). "StAR mRNA and protein levels were significantly increased by infection with recombinant adenovirus." (PMID 23170972, 2012). "The expression of StAR and HSD3B decreased before 24 h post-infection, which was roughly accompanied with decreases in CYP17A1 mRNA expression and P4 production in B.suis.S2-infected cells." (PMID 26904517, 2016). "After infection, RAECs produced both a high StAR mRNA and protein level without inducing any cell toxicity." (PMID 23170972, 2012). "However, infection of theca cells with the AF-1 activating function mutant unable to be phosphorylated by MAP kinases consistently led to a higher induction of CYP11A1, STAR, and INSL3 transcription." (PMID 17176485, 2006).
genetic disorders (2 papers, 2011 to 2022). "For example, the perturbation of StAR functions in the mouse models mimics the same phenotype observed owing to genetic disorders in humans." (PMID 35434552, 2022). "King and colleagues (2002) revealed that the StAR is expressed in glia and neurons of the mouse brain and has a role in the production of neurosteroids supporting STARD8 as a tentative biological role player in genetic disorders related to brain functioning." (PMID 21668950, 2011).
autosomal recessive inherited disorder (1 paper, 2018). "CLAH is an autosomal recessive inherited disorder caused by mutations of the steroidogenic acute regulatory protein (StAR; OMIM 600617) gene." (PMID 30400872, 2018).
bacterial infection (1 paper, 2019). "In summary, we conclude that bacterial infection or LPS exposure-induced ROS decrease progesterone production in porcine granulosa-lutein cells by inhibiting StAR, CYP11A1, and 3β-HSD expressions." (PMID 31178965, 2019).
benign tumors (1 paper, 2020). "When comparing the two subgroups of benign tumors, CYP11B1 and StAR were the steroidogenic proteins that were most differentially expressed in ACAn and ACAc, with lower levels of both proteins found in non-functioning ACA." (PMID 32751564, 2020).
STAR also shares sentences with these, for which no sentence is quoted: Alzheimer disease (3 papers); Cushing syndrome (3); endometrial cancer (3); ) protein deficiency (2); adrenoleukodystrophy (2); Breast Invasive Carcinoma (2); Down syndrome (2); endocrine disorder (2); non-alcoholic steatohepatitis (2); Ovarian cyst (2); type 2 diabetes (2); 3β-hydroxysteroid dehydrogenase deficiency (1); Acidosis (1); adrenal hypoplasia congenita (1); adrenocortical insufficiency (1); alcoholic liver diseases (1); asthenozoospermia (1); Azoospermia (1); benign prostatic hyperplasia (1); campomelic dysplasia (1); dyslipidemia (1); granulosa cell tumor (1); head and neck squamous cell carcinoma (1); hepatic cancer (1); Heterochromia iridis (1); Hyperkalemia (1); Hypertension (1); Hypervolemia (1); Hyponatremia (1); hypospadias (1).
A further 28 diseases each share a sentence with STAR in 1 paper.